PTH (parathyroid hormone)
Description:
Parathyroid hormone elevates calcium level by dissolving the salts in bone and preventing their renal excretion. Acts by binding to its receptor, PTH1R, activating G protein-coupled receptor signaling. Stimulates [1-14C]-2-deoxy-D-glucose (2DG) transport and glycogen synthesis in osteoblastic cells.
Synonyms: PTH1; FIH1
Tractability: Small molecule: a structure with a bound ligand is known. Antibody: UniProt places it where antibodies can reach, with high confidence; its Gene Ontology location is reachable by antibodies, with high confidence; UniProt predicts a signal peptide or a membrane-spanning region.
Gene: Protein-coding gene on chromosome 11 (13,492,054 to 13,496,181, reverse strand). Ensembl gene ENSG00000152266.
Subcellular location: Secreted
Pathways (Reactome):
Signal Transduction: Class B/2 (Secretin family receptors); G alpha (s) signalling events
Gene Ontology:
Molecular function: hormone activity; peptide hormone receptor binding; protein binding; receptor ligand activity; type 1 parathyroid hormone receptor binding; parathyroid hormone receptor binding
Biological process: adenylate cyclase-activating G protein-coupled receptor signaling pathway; G protein-coupled receptor signaling pathway; macromolecule biosynthetic process; negative regulation of gene expression; positive regulation of bone mineralization; positive regulation of D-glucose import; positive regulation of glycogen biosynthetic process; positive regulation of inositol phosphate biosynthetic process; positive regulation of transcription by RNA polymerase II; regulation of gene expression; bone resorption; cAMP metabolic process; cell-cell signaling; hormone-mediated apoptotic signaling pathway; intracellular calcium ion homeostasis; skeletal system development; bone mineralization; calcium ion homeostasis; magnesium ion homeostasis; negative regulation of bone mineralization involved in bone maturation; negative regulation of chondrocyte differentiation; phosphate ion homeostasis; positive regulation of gene expression; positive regulation of ossification; response to cadmium ion; and 8 more
Cellular component: extracellular region
Genetic constraint (gnomAD): Loss-of-function variants: 5 observed, 7.92 expected, observed/expected ratio (o/e) 0.63, 90% interval 0.33 to 1.32. That is too few expected variants to judge how well the gene tolerates losing a copy. Missense variants: 107 observed, 124.24 expected, observed/expected ratio (o/e) 0.86, 90% interval 0.74 to 1.01. Synonymous variants: 41 observed, 41.09 expected, observed/expected ratio (o/e) 1, 90% interval 0.78 to 1.29.
Homologues: Orthologues: chimpanzee PTH (100% identical), macaque PTH (97% identical), dog PTH (86% identical), pig PTH (82% identical), rabbit PTH (77% identical), rat Pth (71% identical), mouse Pth (68% identical), guinea pig PTH (66% identical), zebrafish pth1b (23% identical), zebrafish pth1a (22% identical).
Diseases named in the same sentence as PTH in open-access papers:
PTH is named in the same sentence as 770 diseases in open-access papers, as found by Europe PMC text mining. Sharing a sentence is not in itself a finding about the gene and the disease. The quoted sentences say what the papers report.
Hypercalcemia (1,187 papers, 1989 to 2026). An abnormally increased calcium concentration in the blood. "As with other causes of PHPT, the hypercalcemia observed in PC results from excessive and autonomous secretion of parathyroid hormone (PTH)." (PMID 41568161, 2026). "This case highlights the diagnostic complexities of non-PTH-mediated hypercalcemia and underscores the importance of a comprehensive workup, including medication review, laboratory tests, radiography, and biopsy, with consideration for excisional biopsy." (PMID 41756472, 2026). "In this case, RCC with sarcomatoid changes was detected by biopsy, and elevated PTHrP and suppressed PTH were observed, indicating hypercalcemia caused by PTHrP‐producing renal cell carcinoma." (PMID 41567516, 2026). "Typically, hypercalcemia is associated with increased urinary calcium excretion mediated by the PTH." (PMID 41503412, 2026). "Subsequent biochemical evaluation revealed hypercalcemia with suppressed parathyroid hormone levels and associated renal dysfunction, prompting further investigation." (PMID 42158759, 2026). "Granuloma-mediated hypercalcemia is an uncommon cause of parathyroid hormone-independent hypercalcemia and is usually associated with sarcoidosis, chronic infection, or other inflammatory disorders." (PMID 42109939, 2026). "The overall findings supported silicone-induced granulomatous lymphadenopathy as the cause of parathyroid hormone-independent hypercalcemia." (PMID 42109939, 2026). "These cases demonstrate the importance of recognizing immune checkpoint inhibitors as potential causes of parathyroid hormone (PTH)-independent hypercalcemia." (PMID 41868268, 2026). "Primary hyperparathyroidism (PHPT) is characterized by excessive secretion of parathyroid hormone (PTH) and is the most common cause of hypercalcemia." (PMID 41502796, 2026). "Persistence of hypercalcemia after surgical treatment and normalisation of PTH levels required further diagnostic search and exclusion of other causes of hypercalcemia." (PMID 41640160, 2026). "Laboratory evaluation revealed severe hypothyroidism and marked non-PTH-mediated hypercalcemia with associated acute renal failure." (PMID 42317881, 2026). "A recent RCT in CKD patients with SHPT treated with extended-release calcifediol (ERC) reported that adjunctive active vitamin D further reduced PTH levels by 35% but caused hypercalcemia and impaired kidney function." (PMID 41373702, 2025). "Bone profile reveals hypercalcemia with suppressed parathyroid hormone, associated with low 25-hydroxy vitamin D levels, suspicious for malignancy; however, these parameters were normal on a repeat blood test." (PMID 41404451, 2025). "Fuller Albright initially identified humoral hypercalcaemia of malignancy, suggesting its association with either parathyroid hormone (PTH) or a comparable peptide." (PMID 40142228, 2025). "While undergoing further investigations to ascertain the cause of her PTH-independent hypercalcemia, her corrected calcium remained persistently elevated above 3.0 mmol/L (12 mg/dL) for more than 5 weeks." (PMID 39906901, 2025). "Herein, in the reviewed cases, all patients exhibited hypercalcemia, which is the hallmark of primary hyperparathyroidism, along with elevated levels of PTH." (PMID 41018270, 2025). "Excessive secretion of parathyroid hormone (PTH) can cause hypercalcaemia, leading to a variety of complications, such as renal calculus, chronic kidney failure, severe osteoporosis, and even hypercalcaemic crisis." (PMID 40525887, 2025). "It is often characterized by normal calcemia or moderate hypercalcemia associated with elevated levels of PTH, leading to pHPT." (PMID 40657234, 2025). "Primary hyperparathyroidism (PHPT) is an excessive secretion of PTH caused by a defect in parathyroid cells, insensitive to the suppressive effects of hypercalcemia." (PMID 41427056, 2025).
Hypercalcemia (continued). "The second theory describes a direct insult to the parathyroid glands by lithium, resulting in either a parathyroid adenoma or parathyroid gland hyperplasia, both causing raised serum PTH and subsequent hypercalcaemia." (PMID 41185877, 2025). "Serum biomarkers, such as PTH and PTHrP, further aid in differentiating malignancy-associated hypercalcemia from primary hyperparathyroidism." (PMID 40337388, 2025). "Blood tests can show the most common paraneoplastic syndrome, hypercalcemia, most often linked precisely to the presence of lymphoma and resulting from the production of PTH-related peptides (PTH-rPs) by T-cell lymphoblasts." (PMID 40002191, 2025). "In general, PTH therapy was associated with reductions in serum phosphate, but increased incidence of hypercalcemia." (PMID 40177730, 2025). "The causes of hypercalcaemia can be broadly divided into parathyroid hormone (PTH)-mediated, calcitriol-mediated, malignancy-related and other rare mechanisms." (PMID 40709165, 2025). "In normal physiology, PTH secretion is under tight control by the calcium-sensing receptor in a feedback system whereby hypocalcemia causes and hypercalcemia suppresses secretion of PTH." (PMID 41473615, 2025). "From a diagnostic perspective, the causes of hypercalcemia can be divided into the following categories: PTH-dependent and PTH-independent." (PMID 41009532, 2025). "A whole-body CT neck, chest, abdomen, and pelvis was done in view of the weight loss, hypercalcemia with suppressed PTH, and due to the possible association between dermatomyositis and malignancy." (PMID 41404451, 2025). "Based on the presence of target organ damage directly caused by hypercalcemia or PTH overproduction, PHPT can be clearly differentiated into symptomatic PHPT and asymptomatic PHPT." (PMID 41210508, 2025). "The underlying pathogenic pathways linking hypercalcemia and parathyroid hormone (PTH) excess to the co-presence of the neuropsychiatric symptoms are poorly understood." (PMID 39997061, 2025). "PHPT, which is mainly caused by parathyroid adenoma, leads to hypercalcemia due to the overproduction of PTH." (PMID 41001160, 2025). "Estrogen deficiency reduces the inhibitory effect of PTH-induced bone resorption, leading to hypercalcemia." (PMID 41156271, 2025). "This disparity highlights the heterogeneity in the pathophysiology of RCC-associated hypercalcemia and reinforces the importance of comprehensive diagnostic evaluation that includes measurements of PTH, PTHrP, and vitamin D metabolites." (PMID 40337388, 2025). "In experimental mice, the absence of CYP24A1 causes 50% postnatal mortality due to severe hypercalcemia, accompanied by markedly elevated calcitriol and undetectable PTH." (PMID 40565034, 2025). "Existing literature classifies IgG4-RD–associated hypercalcemia into parathyroid hormone (PTH)-dependent and PTH-independent categories." (PMID 41451224, 2025). "PTHrP is more commonly associated with hypercalcemia in cancer patients, while PTH is more related to conditions like primary hyperparathyroidism." (PMID 40062143, 2025). "Medical management of PC is aimed at reducing the effects of elevated PTH and, in doing so, reducing hypercalcemia, which is the primary cause of morbidity and mortality." (PMID 39963301, 2025). "It involves autonomous parathormone (PTH) secretion and ongoing hypercalcemia even after the initial cause is addressed—usually following successful kidney transplantation." (PMID 41301699, 2025). "Five months later, the patient presented with persistent hyperparathyroidism, accompanied by depression, weakness, and hypercalcemia (2.6 mmol/L) despite normal PTH levels (37.5 pg/mL) and persistent vitamin D deficiency (14.8 ng/mL)." (PMID 40851725, 2025).
Hypercalcemia (continued). "The classic biochemical abnormalities associated with FHH include moderate hypercalcemia, serum PTH levels that are inappropriately normal or elevated, and relatively low urinary calcium, all while the parathyroid glands appear histologically normal." (PMID 40417236, 2025). "PTH-mediated hypercalcemia, which is characterized by elevated PTH levels, is typically caused by primary hyperparathyroidism." (PMID 40610015, 2025). "Primary hyperparathyroidism (PHP) is the most common cause of hypercalcaemia in the outpatient setting and is characterised by autonomous secretion of parathyroid hormone (PTH), leading to renal, skeletal, and neuropsychiatric complications." (PMID 41384172, 2025). "Laboratory tests confirmed hypercalcemia (2.8 mmol/L), normal PTH (47.5 pg/mL), and vitamin D deficiency (11.8 ng/mL)." (PMID 40851725, 2025). "Primary hyperparathyroidism (PHPT) is a disorder of dysregulated parathyroid hormone (PTH) secretion characterized by hypercalcemia with inappropriately elevated PTH levels and increased risk for skeletal and renal disease." (PMID 39677927, 2025). "Primary hyperparathyroidism, the leading cause of hypercalcemia, results from the autonomous production of parathormone (PTH) and ranks as the third most prevalent endocrine disorder." (PMID 40342440, 2025). "Hypercalcemia of malignancy results from tumor-produced parathyroid hormone-related protein (PTHrP) which simulates the actions of parathyroid hormone (PTH) and leads to bone loss and kidney calcium retention." (PMID 40867266, 2025). "Conversely, VDRAs play a key role in controlling SHPT, inhibiting PTH and bone turnover markers; however, they increase the risk of hypercalcemia." (PMID 40177730, 2025). "This case highlights the diagnostic challenges of differentiating lactation-associated hypercalcemia from other causes, including ectopic PTH or PTHrP secretion." (PMID 41487858, 2025). "PTH-independent hypercalcemia is most commonly caused by malignancy or unregulated, extra-renal production of 1,25-dihydroxycholecalciferol (1,25(OH)2D or calcitriol) as occurs in granulomatous and inflammatory conditions." (PMID 40765620, 2025). "The hallmark biochemical abnormality in LIH is hypercalcemia, resulting from increased PTH secretion." (PMID 40851725, 2025). "We reviewed the published literature and excluded primary hyperparathyroidism or ectopic parathyroid hormone secretion as the cause of hypercalcemia in the child." (PMID 39928817, 2025). "It creates a perceived hypercalcemia that further lowers PTH levels and exacerbates hypercalciuria, increasing the risk for nephrocalcinosis, nephrolithiasis and reduced renal function in the long term." (PMID 39607645, 2025). "Men who injected higher amounts of paraffin oil (i.e., > 2.000 mL) exhibited a higher risk of hypercalcemia approx. 12 years later, with a notable compensatory suppression of PTH concentrations." (PMID 40353949, 2025). "Lithium therapy is a cause of PTH-dependent hypercalcemia because of the induced secretion of PTH and subsequent bone resorption." (PMID 39851484, 2025). "Earlier published series described GCM2-related pHPT as a severe variant with very high calcemia and PTH levels series; however, more recent series have found a prevalence of mild hypercalcemia, even with low urinary calcium excretion fraction." (PMID 40329145, 2025). "Suppressed parathyroid hormone (PTH) levels excluded PTH-mediated hypercalcemia (e.g., primary hyperparathyroidism) and among causes of non-PTH-mediated hypercalcemia, malignancies were excluded." (PMID 39906031, 2025). "Patients treated with lithium exhibit a 10% increase in calcium and PTH levels compared to control subjects, along with an elevated risk of developing hypercalcemia." (PMID 40182382, 2025). "It effectively suppresses parathyroid hormone while presenting a lower risk of hypercalcemia compared to calcitriol." (PMID 40290446, 2025).
Hypercalcemia (continued). "Ectopic expression of PTH by tumor cells has been reported in fewer than 30 cases, often contributing to hypercalcemia associated with malignancy." (PMID 40641561, 2025). "We initially assumed that the patient’s acute kidney failure and symptomatology occurred due to hypercalcemia and therefore the diagnostic algorithm primarily included other causes than non-PTH-related causes of hypercalcemia." (PMID 40520830, 2025). "Patients with biallelic CYP24A1 mutations present a PTH-independent hypercalcemia highly variable in its severity, but generally mild outside the settings of early infancy and pregnancy." (PMID 40565034, 2025). "It was found that patients with hypercalcemia and elevated PTH levels were at greater risk of Hypop and kidney stones, but not osteoporosis." (PMID 41509939, 2025). "Primary hyperparathyroidism was suspected in the past as the underlying cause, given her inadequately high-normal parathyroid hormone levels (57 pg/mL, October 2018) despite hypercalcemia (total calcium 3.22 mmol/L)." (PMID 41009532, 2025). "We report the first case to our knowledge of a patient presenting with severe, symptomatic hypercalcemia found to be caused by an ectopic PTH-producing pancreatoblastoma." (PMID 39611185, 2024). "Primary hyperparathyroidism (PHPT) is a systemic disorder characterized by inappropriately elevated parathyroid hormone (PTH) in the presence of high or normal serum calcium, and it is the most common cause of hypercalcemia." (PMID 38280162, 2024). "Failure of the CaSR to recognize elevated serum calcium leads to unopposed PTH activity, causing skeletal demineralization, decreased renal calcium excretion, and severe hypercalcemia, which can be fatal." (PMID 39129820, 2024). "The impaired signaling via the CaSR pathway in these disorders results in a higher set-point for the CaSR, which leads to hypercalcemia in association with plasma PTH concentrations that are in the normal reference range (~ 80%) or elevated." (PMID 38038882, 2024). "Differentiating FHH from primary hyperparathyroidism (PHPT) is crucial since both conditions cause hypercalcemia and elevated PTH levels." (PMID 39246902, 2024). "Apart from vitamin D, the two other drugs that we must consider are lithium and thiazides, as they frequently cause drug-induced hypercalcaemia, albeit with increased PTH levels." (PMID 39434928, 2024). "Excessive PTH-mediated stimulation leads to varying degrees of hypercalcemia, primarily associated with increased bone resorption and enhanced renal calcium reabsorption." (PMID 39519190, 2024). "The diagnostic workup for hypercalcaemia begins with a thorough history, physical examination and measurement of serum parathyroid hormone (PTH) levels." (PMID 39434928, 2024). "In general, primary (and occasionally tertiary) hyperparathyroidism is the most common cause of hypercalcaemia if PTH is high." (PMID 39005653, 2024). "Hypocalciuric hypercalcemia type 1 (OMIM phenotype number 145980) is an AD condition resulting from an inactivating variant in CASR, resulting in lifelong mild to moderate hypercalcemia, inappropriate hypocalciuria, and normal PTH to mild hyperparathyroidism." (PMID 38606357, 2024). "Among other causes of PTH-independent hypercalcaemia, vitamin D-mediated hypercalcaemia should be considered." (PMID 38665259, 2024). "Excessive production and activation of extrarenal 1,25-dihydroxyvitamin D is responsible for 1% of cases, while the rarest cause, accounting for less than 1% of all cancer-related hypercalcemia, is ectopic secretion of parathyroid hormone." (PMID 38920679, 2024). "Like in patients with CYP24A1 mutations, hypercalcaemia, suppressed PTH and inappropriately high 1,25(OH)2D3 are observed." (PMID 38665259, 2024). "Among reported cases, serum calcium and PTH levels vary widely and a more severe hypercalcemia is thought to result from homozygous variants." (PMID 39129820, 2024).